PAX3 (paired box 3)
Diseases named in the same sentence as PAX3 in open-access papers (continued):
Sharing a sentence is not in itself a finding about the gene and the disease.
tumor (continued). "Given the importance of matrix metalloproteinases (MMPs) in tumor metastasis, we also tested the ectopic expression of PAX3 on the expression of MMP-2, –9 and –14 in BCPAP, 8305C and FTC133 cells." (PMID 27458157, 2016). "At the same time, another partner of H19, PAX3 interact with a new ceRNA RP11-356J5.12.1 in tumor state." (PMID 27580177, 2016). "Pax3:Foxo1a mediated a cell survival and tumor re-establishment advantage under the stress condition of irradiation, but not under homeostatic conditions (p = 0.02)." (PMID 24453992, 2014). "At the level of histone marks, we observed a different chromatin state of the Pax3:Foxo1 locus in primary tumor cell cultures with different lineages of origin." (PMID 25030697, 2014). "RT–PCR studies also showed higher levels of Pax3:Foxo1 mRNA levels in murine primary tumor cell cultures derived from Myf6Cre,Pax3(P3Fa/P3Fa) tumors (green) compared with primary tumor cell cultures from Pax7CreER,Pax3(P3Fa/P3Fa) tumors (U31425 and U28285)." (PMID 25030697, 2014). "By quantitative analysis, the mean florescence intensity of eYFP in primary tumor cell cultures derived from Pax7CreER,Pax3(P3Fm/P3Fa) tumors was rarely above the level of C2C12-negative control cells except in rare instances (see the Discussion)." (PMID 25030697, 2014). "Pax3:Foxo1a also tolerizes tumor cells to clinically-established chemotherapy agents and emerging molecularly-targeted agents." (PMID 24453992, 2014). "PAX3 is re-expressed in several tumours which arise from tissues requiring PAX3 regulation during embryonic development 5–6." (PMID 24188742, 2014). "This revealed that Pax3 expression is primarily found within the Olig2-tumor cell compartment of BSG." (PMID 25330836, 2014). "For U23674 tumor cells of the Myf6Cre myoblast lineage, a decrease in both Pax7 and Pax3:Foxo1 mRNA levels upon treatment with all of the drugs was observed, but the effect was more pronounced for HDAC inhibitors." (PMID 25030697, 2014). "On the other hand, mean fluorescence intensity of eYFP in primary cell cultures derived from a Myf6Cre,Pax3(P3Fa/P3Fa) tumor was twofold to threefold higher than control C2C12 cells." (PMID 25030697, 2014). "Higher levels of both H3K4me3 and H3K9Ac active chromatin marks are observed in U23674 and U21459 cells compared with U29415 and U31425 tumor cells, correlating with high versus low Pax3:Foxo1 expression, respectively." (PMID 25030697, 2014). "Although we are unable to determine the percentage of tumor cells expressing both ectopic PDGF-B and Pax3 in this model, the survival advantage associated with both seen here suggests that the tumorigenesis process would select for doubly infected cells." (PMID 25330836, 2014). "While in vitro, Pax3 overexpression inhibits basal apoptosis, this effect is insufficient to induce tumor formation in vivo." (PMID 25330836, 2014). "Collectively, all these findings demonstrate that PAX3 inhibition prevents the transition from G1 to S phase in different tumour cells." (PMID 24188742, 2014). "When murine and human tumor cultures were treated with 2 μM entinostat for 72 h, a pronounced reduction in Pax3:Foxo1 protein levels was observed." (PMID 25030697, 2014). "Currently, PAX-3 along with MCAM appears to be a useful biomarker for assessing tumor load and the effectiveness of treatment in later stage disease." (PMID 24069584, 2013). "Pax3 is a known developmental marker expressed during muscle and brain development, repressed in adult tissue and connected to tumor formation and a poor overall survival." (PMID 21602936, 2011). "Even if the number of samples was low for each subset, a statistical analysis showed a significant P value between (Pax3+) and (Pax7+) and between (Pax+) and (Pax−) tumours, 0.05 and 0.0005 respectively." (PMID 21437224, 2011).
tumor (continued). "Alveolar tumours typically harbour one of the two characterised chromosomal translocations that juxtapose PAX gene family member PAX3 or PAX7 with the Forkhead-related FKHR (FOXO1A) gene." (PMID 12865925, 2003). "Tumours of the alveolar subtype frequently harbour one of two characteristic translocations that juxtapose PAX3 or PAX7, and the forkhead-related gene FKHR (FOXO1A)." (PMID 12865925, 2003). "As expected, expression of the fusion genes was restricted to tumours known to harbour the relevant translocation, with relative expression levels of PAX3-FKHR varying between 0.3- and 3.1-fold and those for PAX7-FKHR between 0.8- and 2.1-fold." (PMID 12865925, 2003). "PAX3, PAX5, and PAX8 are mainly associated with immune checkpoint expression, including PD-L1 and TIGIT, while PAX6 is linked to microsatellite instability and tumor mutational burden, implicating it in genomic dysregulation." (PMID 41752124, 2026). "Furthermore, we observed that all the tumours with weak expression of Pax3::Foxo1 were significantly enriched in the MR2 subset compared with the MR1 subset (p = 0.015)." (PMID 39812007, 2025). "Another study identified PAX3::NCOA2 in a patient tumor diagnosed with embryonal RMS." (PMID 40599857, 2025). "In mouse FN RMS tumours (with low or no Pax3::Foxo1), our study did not identify an association between other driver mutations and DNA methylation." (PMID 39812007, 2025). "Notably, Myf6Cre showed the highest tumor incidence, indicating that Pax3::Foxo1 expression in specific lineages can drive more aggressive tumor behavior." (PMID 40599857, 2025). "In contrast, RMS tumours in which a Pax3::Foxo1 fusion is directed to the Pax7 lineage do not demonstrate differing methylation from RMS tumours in which other mutations are directed to the Pax7 lineage." (PMID 39812007, 2025). "Of note, some of these Pax3::Foxo1 target genes are hypomethylated and others are hypermethylated between FP and FN tumours, and similarly some are underexpressed and some are overexpressed between these tumour groups." (PMID 39812007, 2025). "Initial examination of these clusters/subsets revealed that all GEMM tumours in ML clusters corresponded to Pax3::Foxo1 in one of three lineages (Myf5, Myf6, and Pax3) while all tumours in MR1 corresponded to DNA alterations other than Pax3::Foxo1 in these same three lineages." (PMID 39812007, 2025). "Because of the interconnected nature of myogenic TFs and the genes they regulate, targeting a specific core regulatory TF, like MYOD1, or PAX3/7-FOXO1 is likely to collapse the tumor transcriptome resulting in terminal differentiation of tumor cells or tumor cell death." (PMID 39902277, 2024). "The intensity of pax3a:EGFP in the zRMS larvae suggests that pax3a is highly expressed in zRMS tumours and indicates that Pax3 may play a role in zRMS tumourigenesis." (PMID 36229514, 2022). "PAX3 is a transcription factor controlling the differentiation of melanocytic, neural and myogenic cell lineage and has emerged as a potential oncogene in several different neoplasms, among them BSNS." (PMID 36292216, 2022). "Interestingly, our results showed a significant delay in tumour growth in pax3a−/−;pax3b−/− mutants at 10 and 15 dpf, suggesting an important role of pax3 genes in tumour progression." (PMID 36229514, 2022). "However, re-expression of pax3 in differentiated adult tissues, that require Pax3 function during embryonic development, leads to tumour formation." (PMID 36229514, 2022). "Heterogeneous expression of PAX3:FOXO1 at the single cell level may provide a critical advantage during tumor progression." (PMID 34187933, 2021). "The tumor expressed a PAX3/PAX7-FOXO1 FT in 33 patients over 45 tested (73%)." (PMID 35186818, 2021). "Furthermore, PAX3 was upregulated in tumor tissues compared with normal tissues, and there was a reverse correlation between miR-299-3p and PAX3 expression levels in GC tissues." (PMID 33817318, 2021).
tumor (continued). "In our series all OLIG2 positive tumours were PAX3/7-FOXO1 fusion positive." (PMID 31493794, 2019). "PAX3/7-FOXO1 fusion may be detected by real-time RT-PCR where frozen tumour tissue is available, but this approach is challenging when using formalin-fixed, paraffin-embedded (FFPE) material." (PMID 31493794, 2019). "The PAX3 is highly expressed with the increase in tumor WHO grade." (PMID 29937714, 2018). "One of the major unknowns in the study of ARMS is the nature of the cell that originally suffered the PAX3:FOXO1 chromosomal translocation leading to tumour development." (PMID 28615069, 2017). "We propose that PAX3 may be involved in a regulatory pathway that influences the slowing of tumour growth and may allow more time for an immune response to be mounted in animals with regressed tumours." (PMID 28341828, 2017). "Our data are consistent with some other models of metastatic and/or more aggressive cancers exemplifying tumor promoting genes like urokinase plasminogen activator (uPA), PAX3 and Ezrin that are less methylated and/or more highly expressed in the more aggressive cancer forms." (PMID 25586191, 2015). "However, high RTK expression correlates with inferior outcome in PAX3/7-FOXO1-negative tumours as well, suggesting that this class of proteins likely contributes to the growth and survival of this malignancy." (PMID 26147305, 2015). "Altogether, these data suggest that the observed differences in Pax3:Foxo1 mRNA levels could be explained by a different chromatin state in these loci depending on the tumor lineage of origin." (PMID 25030697, 2014). "Interestingly, U29415 tumor cells of Pax7CreER satellite cell lineage showed a paradoxical increase in mRNA levels of Pax7 and Pax3:Foxo1 when treated with 20 μM 5-Aza-2′deoxycytidine, 15 μM entinostat, and 5 μM SAHA." (PMID 25030697, 2014). "The functional discrepancies could be explained by varying contexts of genetic alterations, differences between mouse and human tumor biology, or an inhibitory effect on Pax3 expression or function of the cerebral cortex stroma in mice." (PMID 25330836, 2014). "However, FACS analysis over time revealed that the eYFP signal of Pax3:Foxo1alow and Pax3:Foxo1ahigh tended towards the mean eYFP fluorescence intensity of unsorted tumor cells with time and/or cell divisions." (PMID 24453992, 2014). "Similarly, Pax3:Foxo1a knockdown sensitized tumor cells to siRNA inhibition of downstream signaling mediators of acquired imatinib resistance." (PMID 24453992, 2014). "As Pax3 is a developmental transcription factor whose expression normally decreases as differentiation proceeds, we next investigated whether Pax3 is expressed at the time of tumor initiation in the brainstem, which in our mouse model is P2-4." (PMID 25330836, 2014). "Using a conditional genetic mouse model as well as human tumor cell lines, we show that that Pax3:Foxo1a expression is enriched in G2 and triggers a transcriptional program conducive to checkpoint adaptation under stress conditions such as irradiation in vitro and in vivo." (PMID 24453992, 2014). "We compared expression of Pax3:Foxo1a expressing primary tumor cell cultures with or without Rb1 loss (n = 3 biological replicates each) to proliferating or differentiating C2C12 myoblasts as a control for the aRMS cell of origin." (PMID 24274149, 2013). "Additionally, oncogenic transcription factor Pax3 is closely involved in the regulation of ST8SiaII in tumour cells: engineered over-expression of this gene is known to increase ST8SiaII mRNA levels by up to four-fold, whereas ST8SiaIV mRNA is not affected." (PMID 23951351, 2013).
tumor (continued). "PAX3- and PAX7-FKHR gene fusion, mutations in the von Hippel Lindau tumor suppressor gene, hypoxia in the tumor microenvironment, NF-κB, and inflammatory cytokines such as vascular endothelial growth factor and tumor necrosis factor alpha, have all been implicated in CXCR4 overexpression." (PMID 21880153, 2011). "(Pax+) tumours, particularly those (Pax3+) overexpressed all these miRNAs." (PMID 21437224, 2011). "These tumours are thought to originate from a multipotential mesenchymal cell type and are correlated with translocations between chromosomes 1 or 2 and chromosome 13, resulting in the generation of Pax3- or Pax7- forkhead (Pax3-7/FKHR) chimaeric genes." (PMID 18289368, 2008). "Of note, expression of DNMTs was found to be lower in alveolar RMS tumours (predominantly FP) compared with embryonal RMS tumours (generally FN), and thus we propose that PAX3::FOXO1 may contribute to this expression difference and thereby influence the DNA methylation pattern." (PMID 39812007, 2025). "Additionally, oncogenic fusion genes such as PAX3:FOXO1 have been implicated in suppressing interferon signaling pathways and reducing the expression of antigen presentation machinery, further impairing immune recognition of tumor cells." (PMID 41007114, 2025). "PAX3 inactivation may abrogate tumor suppression, and promote thyroid tumorgenesis." (PMID 27458157, 2016). "Collectively, our data suggest that PAX3 may exert tumor suppressor function." (PMID 27458157, 2016). "With regard to tumor initiation, our data suggest that the Pax3 chromatin structure may be closed (and relatively inaccessible to events like Cre/LoxP DNA recombination) and show that transcription from the Pax3 locus is inactive in tumor cells of this satellite cell lineage." (PMID 25030697, 2014). "Thus, the Pax7CreER postnatal satellite cell lineage did not appear to be poised for giving rise to aRMS when the Pax3:Foxo1 oncogene at the Pax3 locus is triggered; instead, cells of Pax7CreER satellite cell lineage had a tendency to give a spindle cell-like tumor phenotype." (PMID 25030697, 2014). "Therefore, PAX3 re-expression is important for tumour cell proliferation." (PMID 24188742, 2014). "The potential of FKHR-PAX3 to escape negative regulation by PAX3-FKHR might be an important feature at the start of cell transformation process to enable a critical mass of these “transformable starter” cells to accumulate at the site of an emerging tumor." (PMID 23799156, 2013). "In the tumor microarray data, 1,693 probe-sets (1,115 upregulated and 578 downregulated) on the HG U133A platform were either significantly upregulated or downregulated in the PAX3(+/−Q)-FOXO1-positive ARMS tumors (n=16) compared to the fusion-negative ERMS tumors (n=15)." (PMID 23733015, 2013). "However, this percentage decreased in patients following surgical removal of metastatic lesions, suggesting PAX3 expression could be used to monitor the tumor load in patients undergoing surgery and other treatments." (PMID 24069584, 2013). "PAX3-and PAX7-FKHR gene fusion, mutations in the von Hippel Lindau gene, hypoxic conditions in the tumor microenvironment, NF-κB, vascular endothelial growth factor, and tumor necrosis factor alpha have all been found to regulate CXCR4 overexpression in different tumor cells." (PMID 23472074, 2013). "It was hypothesized that PAX3-FOXO1 expression from the PAX3 control sequences was insufficient to cause ARMS formation, and downstream regions of the FOXO1 locus may be required to induce sufficient PAX3-FOXO1 expression to induce tumor development." (PMID 23206814, 2012). "PAX3::FOXO1 activity was augmented by MYCN overexpression, and xenografting these cells resulted in a faster tumor growth rate than PAX3::FOXO1 alone." (PMID 40599857, 2025).
tumor (continued). "For tumor size, tumor invasiveness (T1 vs. T2) and FOXO1 fusion partner (PAX3 vs. PAX7) a significant correlation was observed for OS." (PMID 39781573, 2025). "Moreover, PAX3 expression has emerged as a potential determinant of therapeutic sensitivity, with its levels significantly correlating with the responsiveness to multiple anti-tumor drugs, including vorinostat, doramapimod, linsitinib, and tamoxifen, among others." (PMID 41180518, 2025). "PAX3::FOXO1/sgTrp53 tumors occurred unilaterally, with an average tumor-free survival time of 100 days and a 40% penetrance rate." (PMID 40523919, 2025). "Elevated ALK transcript levels were correlated with several adverse clinical features, including a PAX3/7–FOXO1-positive histology, an advanced tumor stage, and a larger tumor size at diagnosis." (PMID 40508013, 2025). "Overall, moderate agreement (κ = 0.44, 95% CI: 0.11–0.77) was demonstrated between the presence of Myf6 lineage and high Pax3::Foxo1 expression, implicating an interaction between Myf6 lineage and Pax3::Foxo1 during the development of these FP RMS tumours." (PMID 39812007, 2025). "In a follow-up study, PAX3::FOXO1 genetically cooperates with transcriptional target, FGF8 (with constitutive MYCN expression), to enhance cell proliferation and tumor growth." (PMID 40599857, 2025). "Pediatric RMS, especially the alveolar subtype with PAX3:FOXO1 or PAX7:FOXO1 fusions, often exhibits a notably immune-suppressing environment that impairs effective anti-tumor immune responses." (PMID 41007114, 2025). "Intriguingly, while there are limited genetic perturbations in FP-RMS, it appears that the PAX3/7-FOXO1 fusion protein alters the ability of MRFs to activate a myogenic program, thus facilitating tumor proliferation." (PMID 39902277, 2024). "The PAX3::FOXO1 fusion protein is a key regulator of FP-RMS oncogenesis and its unique expression in tumor tissues supports development of direct inhibitors." (PMID 37732905, 2023). "The gene coding for the transcription factor SIX1, co-expressed with PAX3 and PAX7 in myogenic precursors, is highly expressed in human RMS tumours and has been reported to be a regulator of metastasis in mice models for RMS21." (PMID 36229514, 2022). "MiR-27a is another tumor suppressive miRNA in RMS that can target PAX3-FOXO1 by binding to PAX3 mRNA as evidenced in mouse and human cells and can target both PAX3 and PAX7 mRNA in muscle cells." (PMID 36033507, 2022). "PAX3:FOXO1 low cell states are characterized by more efficient adhesion, migration and tumor-propagating capacity." (PMID 34187933, 2021). "Our results obviously need further confirmation on the larger series of RMS tumours, nevertheless already obtained results indicate that positive OLIG2 alone or in association with other markers may serve as a substitute for the presence of PAX3/7-FOXO1 gene fusion." (PMID 31493794, 2019). "Low-coverage WGR of individuals showing tumor regression and those that succumbed to the disease enabled a genome-wide association study to be undertaken, which identified two genomic regions that may be associated with resistance to DFTD including PAX3 and TLL1 loci." (PMID 31717707, 2019). "In the normal state, H19 compete with ZEB1 and PAX3, while the interaction between H19 and ZEB1 is ‘switch off’ in the tumor." (PMID 27580177, 2016). "The upregulation of other homeobox transcription factors was also observed by us in cases of infratentorial tumor, which was shown to be connected with Iroquois homeobox transcription factors (IRX1, IRX2, IRX3, IRX5) and the PAX3 gene." (PMID 26497896, 2015).